GTPBP8 (GTP binding protein 8)
Synonyms: HSPC135; MRX8
Tractability: PROTAC: ubiquitination databases record sites on it; its protein half-life has been measured.
Gene: Protein-coding gene on chromosome 3 (112,990,978 to 113,015,060, forward strand). Ensembl gene ENSG00000163607.
Subcellular location (Human Protein Atlas): Mitochondria
Gene Ontology:
Molecular function: protein binding; GTP binding
Cellular component: mitochondrion
Genetic constraint (gnomAD): Loss-of-function variants: 6 observed, 7.71 expected, observed/expected ratio (o/e) 0.78, 90% interval 0.42 to 1.51. That is too few expected variants to judge how well the gene tolerates losing a copy. Missense variants: 209 observed, 161.53 expected, observed/expected ratio (o/e) 1.29, 90% interval 1.15 to 1.45. Synonymous variants: 91 observed, 76.98 expected, observed/expected ratio (o/e) 1.18, 90% interval 1 to 1.41.
Homologues: Orthologues: chimpanzee GTPBP8 (98% identical), macaque GTPBP8 (95% identical), rabbit GTPBP8 (80% identical), dog GTPBP8 (79% identical), guinea pig GTPBP8 (78% identical), mouse Gtpbp8 (76% identical), pig GTPBP8 (75% identical), rat Gtpbp8 (75% identical), tropical clawed frog gtpbp8 (57% identical), zebrafish gtpbp8 (54% identical).
Diseases named in the same sentence as GTPBP8 in open-access papers:
GTPBP8 is named in the same sentence as 3 diseases in open-access papers, as found by Europe PMC text mining. Sharing a sentence is not in itself a finding about the gene and the disease. The quoted sentences say what the papers report.
osteosarcoma (2 papers, 2023 to 2024). A usually aggressive malignant bone-forming mesenchymal neoplasm, predominantly affecting adolescents and young adults. "Expression of myc- or green fluorescent protein (GFP)-tagged GTPBP8 in human osteosarcoma cells (U2OS) displayed a similar intracellular distribution, co-localizing with the mitochondrial proteins TOM20 and COXIV." (PMID 37971521, 2023). "To confirm GTPBP8 mitochondrial subcellular localization (as it has not yet been annotated in the human MitoCarta3.0 dataset), we performed immunofluorescence imaging of human 143B osteosarcoma (HOS) cells transiently expressing a C-terminal FLAG-tagged GTPBP8 cDNA construct (GTPBP8::FLAG)." (PMID 38969660, 2024).
breast carcinoma (1 paper, 2022). "This suggests that variation in CATG00000061359 may influence the expression of GTPBP8 in breast cancer." (PMID 35672401, 2022).
infection (1 paper, 2025). The state of being infected such as from the introduction of a foreign agent such as serum, vaccine, antigenic substance or organism. "Finally, GTPBP8, a mitochondrial GTPase required for ribosome assembly, suggests that mitochondrial protein synthesis may be altered in prolonged infection." (PMID 41366310, 2025).